NF2 (NF2, moesin-ezrin-radixin like (MERLIN) tumor suppressor)
Diseases named in the same sentence as NF2 in open-access papers (continued):
Sharing a sentence is not in itself a finding about the gene and the disease.
meningioma (continued). "In anaplastic meningioma, however, we found a more uniform driver landscape dominated by deleterious mutations in NF2." (PMID 30202034, 2018). "Next-generation sequencing techniques have enabled characterization of the genomic landscape of primary meningiomas, including the discovery of several driver mutations in genes including NF2, TRAF7, KLF4, AKT1, and SMO." (PMID 29764516, 2018). "We also performed Sanger sequencing to check for the presence of mutations previously reported in meningioma driver genes, including regions of NF2, AKT1, TRAF7, KLF4, SMO, and the TERT promoter." (PMID 28552950, 2017). "Meningiomas with these alterations carry a significantly higher risk of being atypical as compared with non-NF2 meningiomas, including TRAF7 (with PI3K or KLF4 alterations), Hedgehog or POLR2A mutant tumours." (PMID 28195122, 2017). "When present, NF2 alterations are believed to be the initiating event in meningiomagenesis, in part because germline alterations in NF2 cause Neurofibromatosis 2, characterized by frequent meningiomas and schwannomas." (PMID 28713588, 2017). "Loss of chromosome 22, which contains the known meningioma tumor suppressor NF2, was observed in Ben-Men-1 and CH157-MN." (PMID 28552950, 2017). "Across the cohort of 702 high-grade and low-grade meningiomas from unique patients, loss of chromosome 22 and mutations in NF2 tended to co-occur (p < 2 × 10−16)." (PMID 28713588, 2017). "The most common genetic mutation in meningiomas is NF2 inactivation, which is observed not only in NF2-associated tumors, but also in 47 to 72% of sporadic meningiomas, and is thus considered an integral step for meningioma tumor initiation." (PMID 28193203, 2017). "Of the 88 histologically atypical meningiomas, 75% contained NF2 mutations, while the remaining 9% were TRAF7/PI3K mutant and 16% did not harbour a mutation in the previously established meningioma genes." (PMID 28195122, 2017). "On the basis of correction for mutational background by considering only the NF2 mutant meningiomas, we calculated atypical tumours to have a 2.19 times greater risk to be CNV-high (P=0.001, Fisher’s exact test)." (PMID 28195122, 2017). "We further analyzed 35 meningiomas with the whole exome or whole genome sequencing data, the frequency analysis of genetic alteration reveals increased NF2 or chr22 loss in human meningiomas with higher OGN mRNA expression." (PMID 28923059, 2017). "As a result, most of the previously reported meningioma mutations (NF2, TRAF7, NOTCH2, SMARCB1, CHEK2 and AKT1) were also detected in this study." (PMID 28177878, 2017). "Loss of function of the tumor suppressor NF2 plays a driver role in the meningioma initiation and development." (PMID 28923059, 2017). "The major known genetic contributor to meningioma formation was NF2, which is disrupted by mutation or loss in about 50% of tumors." (PMID 28177878, 2017). "Recent work has demonstrated that there exist two broad classes of meningiomas based on their mutational profile: those driven by NF2 inactivation, and those with non-NF2 driver gene alterations, such as mTOR and Hedgehog pathway alterations." (PMID 28552950, 2017). "To date, the most common alterations in sporadic meningiomas are NF2 mutations or loss of 22q, with non-NF2 mutant meningiomas harboring mutations in in AKT1, TRAF7, KLF4, POLR2A and SMO16–18." (PMID 28775249, 2017). "Several biological pathways in meningioma oncogenesis, including loss of NF2 and mutation of AKT1, are postulated to exhibit their oncogenic effects through activation of the mTOR mitogenic pathway, leading to uncontrolled neoplastic growth." (PMID 28923059, 2017). "Unsupervised hierarchical clustering of miRNA expression profiles correlated well with being benign versus atypical, CNV status, and also with the underlying meningioma driver mutation, clearly separating NF2 mutants from non-NF2 meningiomas." (PMID 28195122, 2017).
meningioma (continued). "Our study demonstrates that RIMs possess a mutational signature that is distinct from sporadic meningioma, displaying NF2 inactivation through structural rearrangements." (PMID 28775249, 2017). "Our observations confirm previous findings that inactivation of NF2 is likely to be the primary step in NF2-associated meningioma formation." (PMID 28193203, 2017). "A more recent study used single nucleotide polymorphism array analysis to report increased chromosomal instability with increasing grade in NF2-associated meningiomas." (PMID 28193203, 2017). "We also identified mutations in known meningioma driver genes, including two mutations in NF2 and a TRAF7G536S missense mutation, which were confirmed by Sanger sequencing." (PMID 28552950, 2017). "In a distinct subgroup of CNV-low but hypermethylated NF2 mutant atypical meningiomas, we observed recurrent SMARCB1 mutations." (PMID 28195122, 2017). "Three cases (case 1, 3 & 7) carried loss of chromosome 22 and deletions of three known meningioma-driver genes (NF2, CHEK2 and SMARCB1)." (PMID 28177878, 2017). "NF2-associated meningiomas are rarer than their sporadic counterparts and far fewer studies have investigated the genetics underlying their initiation and progression." (PMID 28193203, 2017). "Previously, the only genetic driver of meningiomas to be identified was bi-allelic mutation or loss of the tumor suppressor gene neurofibromatosis 2 (NF2) on chromosome 22, encoding the protein Merlin." (PMID 28177878, 2017). "No CNV events were significantly associated with atypical non-NF2 meningiomas compared with benign non-NF2 samples." (PMID 28195122, 2017). "Because of the high prevalence of NF2 alterations in the atypical cohort, a tumour harbouring NF2 loss has a 3.78 times greater risk to be atypical compared with a non-NF2 meningioma (P=2.2 × 10−10, Fisher’s exact test)." (PMID 28195122, 2017). "To characterize specific transcriptional changes associated with atypical tumours, we next corrected for the underlying meningioma driver mutation by dividing the cohort into NF2 and non-NF2 subgroups as before." (PMID 28195122, 2017). "Here, we show that the majority of primary (de novo) atypical meningiomas display loss of NF2, which co-occurs either with genomic instability or recurrent SMARCB1 mutations." (PMID 28195122, 2017). "Although bilateral vestibular schwannomas (VS) are a diagnostic hallmark of the disorder, NF2 patients typically develop multiple meningiomas, ependymomas and other schwannomas as well." (PMID 28427224, 2017). "Several DE changes are widely accepted for human meningiomas, with association to genetic alterations of the type 2 neurofibromatosis gene (NF2; chromosome 22q) being the best documented." (PMID 29073243, 2017). "Mutation occurred in NF2, the hippo signaling pathway upstream gene, causing acoustic neuromas and meningiomas in the brain." (PMID 28837560, 2017). "The most frequent cytogenetic aberration in benign WHO grade I meningiomas is the partial or complete loss of chromosome 22 that is associated with the loss of the neurofibromatosis 2 (NF2) gene." (PMID 28340489, 2017). "Focally, inactivation of NF2, through copy loss or mutation, occurs in 70–80% of fibroblastic and transitional meningiomas." (PMID 27458586, 2016). "Oncogenic mutations in PIK3CA are observed in ~7% of non-NF2-mutant meningiomas, and occur mutually exclusive of AKT1 and SMO mutations, although they frequently co-occur with TRAF7 mutations." (PMID 27458586, 2016). "Meningioma represents one of the first tumors associated with a genomic driver, with the initial identification of neurofibromin (NF2), the causative gene for neurofibromatosis 2 (NF2), in which 50–75% of patients develop one or more meningiomas." (PMID 27458586, 2016). "In comparison, convexity meningiomas are more likely to express NF2 mutations and loss of heterozygosity of chromosome 22." (PMID 27458586, 2016).
meningioma (continued). "Mutations and loss of heterozygosity (LOH) of the NF2 locus have also been detected at high frequency in various tumors of the nervous system, including sporadic schwannomas, meningiomas and ependymomas." (PMID 27363027, 2016). "Meningiomas are a principal feature of neurofibromatosis type 2 (NF2), a rare autosomal dominant disorder caused by germline mutation in the NF2 gene on 22q12.2." (PMID 27429002, 2016). "Loss of merlin is a consistent finding in all NF2 associated meningiomas and meningiomas can be considered as tumours evolved due to the loss of merlin, together with schwannomas, hamartomas and ependymomas." (PMID 27429002, 2016). "Mutations of NF2 in sporadic meningiomas show relatively high frequency and usually lead to a truncated protein." (PMID 27429002, 2016). "The NF2 mutations are frequently found in fibrous, transitional and psammomatous but also in atypical and anaplastic meningiomas, whereas meningothelial, secretory and microcystic subtypes rarely harbour NF2 mutations." (PMID 27429002, 2016). "Germline mutation in the NF2 gene is the most commonly identified genetic risk factor for multiple meningioma disease." (PMID 26950155, 2016). "About half of the sporadic meningiomas harbor a mutation in the tumor suppressor gene NF2 encoding merlin that is a critical factor for regulation of contact-dependent inhibition of cell proliferation." (PMID 27096627, 2016). "Reduction of group I Pak activity by genetic or pharmacological means was associated with a partial G1 cell cycle arrest, decreased motility, and deceleration of meningioma growth in NF2-deficient meningioma cell lines." (PMID 25596744, 2015). "Immunoblotting of 4 unrelated patient-derived primary NF2-deficient meningioma (MN) cell lines, as well as 3 NF2-null AC-CRISPR clones revealed increased SGK1 levels compared to control ACs." (PMID 26219339, 2015). "Here we show that PDGF-B overexpression in arachnoid mouse cells induces the development of benign meningiomas synergizing with Nf2 and Cdkn2ab loss for malignant histological progression." (PMID 26418719, 2015). "In line with the unique features associated with NF2 mutation in meningiomas, an association with postmenopausal women tumors carrying monosomy 22 has also been reported recently." (PMID 25965831, 2015). "YAP suppression has been shown to rescue the hyperproliferative phenotypes caused by NF2 inactivation in both mesothelioma and meningioma." (PMID 26389076, 2015). "We previously reported constitutive activation of mTORC1 signaling in NF2-deficient human arachnoidal cells (ACs), in primary meningioma cells and in NF2-associated tumors, meningiomas and schwannomas." (PMID 26219339, 2015). "Here we performed a high-throughput kinome screen to identify kinases responsible for mTORC1 pathway activation in NF2-deficient meningioma cells." (PMID 26219339, 2015). "All Neurofibromatosis 2 (NF2)-associated meningiomas and ~60% of sporadic meningiomas show loss of NF2 tumor suppressor protein." (PMID 26219339, 2015). "While PDGF-B overexpression in addition to Nf2 loss resulted in higher tumor frequency and grade II meningiomas, additional loss of Cdkn2ab also induced malignant grade III meningiomas." (PMID 26418719, 2015). "Here we observed a correlation between PDGFR-B expression and NF2 loss in human meningiomas and their synergy in mouse meningiomagenesis." (PMID 26418719, 2015). "Increased incidence of CNS tumors including schwannoma, meningioma, and ependymoma has been reported in Neurofibromatosis type 2 patients who carry a single mutated NF2 allele." (PMID 25909290, 2015). "We further show elevated expression of SGK1 accompanied by constitutive activation of SGK1 as detected by phosphorylation of its specific target NDRG1, in human arachnoidal and meningioma cells with NF2 loss." (PMID 26219339, 2015). "Tumors associated with NF2 often display more aggressive histologic features than sporadic meningiomas." (PMID 25596744, 2015).
meningioma (continued). "In humans, germline or somatic mutations in one allele of NF2 result in the disease neurofibromatosis type 2, which is associated with schwannomas, meningiomas, and ependymomas." (PMID 26389076, 2015). "A first germline mutation in the SMARCB1 gene will predispose to meningioma, but this will occur only when a somatic mutation in the NF2 gene intervenes." (PMID 26173390, 2015). "In NF2-deficient meningioma cells, inhibition of SGK1 rescues mTORC1 activation, and SGK1 activation is sensitive to dual mTORC1/2 inhibitor AZD2014, but not to rapamycin." (PMID 26219339, 2015). "In conclusion, we demonstrated that in vivo PDGF-B overexpression in mouse arachnoidal cells promotes meningioma initiation and cooperates with Nf2 and Cdkn2ab loss to promote histological meningioma progression." (PMID 26418719, 2015). "PAK1 inhibition also leads to attenuated mTORC1 but not mTORC2 signaling, suggesting that mTORC2/SGK1 and Rac1/PAK1 pathways are independently responsible for mTORC1 activation in NF2-deficient meningiomas." (PMID 26219339, 2015). "mTORC1 is constitutively activated in NF2-associated schwannomas and meningiomas, and rapamycin was shown to block this mTORC1 activation." (PMID 26219339, 2015). "While surgery remains the primary treatment for meningioma patients, development of effective medical therapies for these tumors, in particular those associated with NF2 loss, remains an important goal." (PMID 25596744, 2015). "The majority of WHO grade I meningiomas (50%–60%) have been linked to mutations of the NF2 gene on chromosome 22 (location: q12.2)." (PMID 25485306, 2014). "This is supported by the fact that patients with type II neurofibromatosis, who have constitutional mutations of the NF2 gene on the long arm of chromosome 22 (22q12.2), often present with multiple meningiomas." (PMID 24722350, 2014). "Mutations in the NF2 gene cause Neurofibromatosis Type 2 (NF2), a disorder characterized by the development of schwannomas, meningiomas and ependymomas in the nervous system." (PMID 24259290, 2013). "Despite different mutations involving distinct exons of the NF2 gene were found in each NF2-mutated meningioma case, they led to a truncated protein or a small in frame deletion and therefore, potentially also to a loss of (normal) function of the nf2 protein." (PMID 24171707, 2013). "Here, we analyzed the frequency of both copy number changes involving chromosome 22 and NF2 mutations in 20 sporadic meningiomas using high-density SNP-arrays, interphase-FISH and PCR techniques." (PMID 24171707, 2013). "Because of this and the development of meningiomas in patients with neurofibromatosis carrying mutations of the NF2 gene coded at chromosome 22q12.2, NF2 has long been considered as the most relevant gene targeted by chromosome 22 losses in meningiomas." (PMID 24171707, 2013). "Our results suggest that a minority of NF2-associated meningiomas shrink during bevacizumab therapy and that these responses were of short duration." (PMID 23555840, 2013). "Defects caused by mutations of the NF2 gene give rise to NF2 disease, which is generally characterized by the formation of bilateral vestibular schwannomas and, to a lesser extent, meningiomas and ependymomas." (PMID 22912849, 2012). "Meningiomas in NF2 and approximately 60% of sporadic meningiomas involve inactivation of the NF2 locus, encoding the tumor suppressor merlin on chromosome 22q." (PMID 19589153, 2009). "They found two truncating mutations in meningioma tissue as well as loss of one copy of the NF2 gene by LOH analysis." (PMID 19772601, 2009). "Biallelic inactivation of the neurofibromatosis 2 (NF2) tumor suppressor is associated with meningioma formation in all NF2 patients and 60% of sporadic meningiomas." (PMID 17924978, 2008). "In the present study, we evaluated the effects in meningioma initiation and progression of p16Ink4a loss with retention of p19Arf in synergy with Nf2 loss." (PMID 17924978, 2008).
meningioma (continued). "Previously, we inactivated Nf2 in homozygous conditional knockout mice by adenoviral Cre delivery and showed that Nf2 loss in arachnoid cells is rate‐limiting for meningioma formation." (PMID 17924978, 2008). "Here we have shown that Ink4a nullizygosity enhances the incidence of meningioma formation induced by somatic Nf2 loss in arachnoid cells, and that in mice p16ink4a loss is not a critical event associated with malignant progression of meningioma." (PMID 17924978, 2008). "Biallelic NF2 inactivation also underlies the development of many sporadic schwannomas and meningiomas, as well as malignant mesothelioma, an essentially untreatable cancer." (PMID 17971776, 2008). "We have shown that biallelic loss of Nf2 is rate‐limiting for meningioma development with mice developing a range of meningioma subtypes histologically similar to WHO grade I human meningiomas." (PMID 17924978, 2008). "The higher frequency of en plaque meningiomas in our mouse model is likely caused by the multifocality of Nf2 inactivation induced by diffusion in the subarachnoid space of the highly concentrated adCre vector suspension." (PMID 17924978, 2008). "Sporadic meningiomas were therefore screened for mutations in the NF2 gene, which was found to be frequently inactivated." (PMID 17222329, 2007). "Approximately 50% of NF2 patients suffer from meningiomas, making them the second most frequent neoplasm associated with this tumor syndrome." (PMID 17222329, 2007). "Chromosome 22 DNA copy number status and NF2 gene mutations in a subset of 100 sporadic meningiomas." (PMID 17222329, 2007). "We also analyzed the methylation status of NF2 promoter associated CpGs in order to examine if this mechanism is associated with repressing NF2 transcription in sporadic meningiomas." (PMID 17222329, 2007). "In meningiomas of higher grade, losses of chromosome 22q and 1p have been reported apart from mutations of the NF2 gene, but the genetic idiosyncrasies of PM are too scanty to be useful in making this ominous diagnosis." (PMID 17233924, 2007). "Allelic loss on 22q also is characteristic for meningiomas, however most of these alterations are considered to be associated with mutations of the NF2 gene." (PMID 11161377, 2001). "We previously generated an orthotopic, NF2-deficient meningioma model using the luciferase-expressing Ben-Men-1 cell line established from a sporadic tumor and identified the multikinase inhibitor brigatinib and the mTOR kinase inhibitor INK128 to potently impede tumor growth." (PMID 41417846, 2026). "NF2 mutations are also detectable in sporadic schwannomas, in meningiomas, and, peculiarly, in sporadic malignant mesotheliomas, indicating that the NF2 gene may be a critical growth regulator for all these cell types." (PMID 40725095, 2025). "In this study, the GSE216783 dataset contained 12/15 (80%) VS samples with known NF2 pathogenic variants, and although the NF2 status of the sporadic meningioma from GSE183655 were unavailable, 3/6 (50%) of these were confirmed to have a loss of 22q (the region in which the NF2 gene is located)." (PMID 41437121, 2025). "In addition to NF2 deficient meningiomas, a proportion of meningiomas exhibit normal NF2 expression." (PMID 39894505, 2025). "The application of SPME enabled simple profiling of a wide range of acylcarnitines in meningiomas and showed that the presence of NF2 mutation could alter the acylcarnitine profile." (PMID 40004036, 2025). "In the setting of multiple meningiomas, although NF2-SWN is the most common tumour predisposition condition for people with ≥ 2 meningiomas before age 40, peripheral schwannomas and intracranial meningiomas can be seen in the chromosome 22 condition SMARCB1-SWN." (PMID 41160189, 2025). "In addition, NF2 alterations have been reported to be linked to a worse prognosis in supratentorial CNS WHO grade I meningiomas." (PMID 40815185, 2025).